SF3A2 (splicing factor 3a subunit 2)
Description:
Component of the 17S U2 SnRNP complex of the spliceosome, a large ribonucleoprotein complex that removes introns from transcribed pre-mRNAs. The 17S U2 SnRNP complex (1) directly participates in early spliceosome assembly and (2) mediates recognition of the intron branch site during pre-mRNA splicing by promoting the selection of the pre-mRNA branch-site adenosine, the nucleophile for the first step of splicing. Within the 17S U2 SnRNP complex, SF3A2 is part of the SF3A subcomplex that contributes to the assembly of the 17S U2 snRNP, and the subsequent assembly of the pre-spliceosome 'E' complex and the pre-catalytic spliceosome 'A' complex. Involved in pre-mRNA splicing as a component of pre-catalytic spliceosome 'B' complexes, including the Bact complex. Interacts directly with the duplex formed by U2 snRNA and the intron.
Synonyms: SAP62; SF3a66; PRPF11; Prp11
Tractability: Small molecule: a structure with a bound ligand is known. PROTAC: ubiquitination databases record sites on it; its protein half-life has been measured.
Target class: Other nuclear protein
Gene: Protein-coding gene on chromosome 19 (2,236,823 to 2,248,672, forward strand). Ensembl gene ENSG00000104897.
Subcellular location: Nucleus
Subcellular location (Human Protein Atlas): Nucleoplasm
Pathways (Reactome):
Metabolism of RNA: mRNA Polyadenylation; mRNA Splicing - Major Pathway
Chromatin organization: CHD1 and CHD2 subfamily
Disease: Dengue Virus-Host Interactions
Gene Ontology:
Molecular function: protein binding; RNA binding; nucleic acid binding; zinc ion binding
Biological process: mRNA processing; mRNA splicing, via spliceosome; U2-type prespliceosome assembly; mRNA 3'-splice site recognition; spliceosomal complex assembly; spliceosomal snRNP assembly; positive regulation of neuron projection development
Cellular component: catalytic step 2 spliceosome; nucleoplasm; nucleus; precatalytic spliceosome; spliceosomal complex; U2 snRNP; U2-type catalytic step 1 spliceosome; U2-type precatalytic spliceosome; U2-type spliceosomal complex; U2-type prespliceosome; nuclear speck
Genetic constraint (gnomAD): Loss-of-function variants: 4 observed, 30.34 expected, observed/expected ratio (o/e) 0.13, 90% interval 0.064 to 0.3. The synonymous counts are far from expectation, so gnomAD's model fits this gene poorly and the ratio says little. Missense variants: 262 observed, 376.01 expected, observed/expected ratio (o/e) 0.7, 90% interval 0.63 to 0.77. Synonymous variants: 193 observed, 155.78 expected, observed/expected ratio (o/e) 1.24, 90% interval 1.1 to 1.4.
Homologues: Orthologues: chimpanzee SF3A2 (100% identical), macaque SF3A2 (99% identical), mouse Sf3a2 (97% identical), dog SF3A2 (96% identical), rat Sf3a2 (95% identical), pig SF3A2 (95% identical), guinea pig SF3A2 (94% identical), tropical clawed frog sf3a2 (75% identical), zebrafish sf3a2 (52% identical), Drosophila melanogaster Sf3a2 (45% identical), Caenorhabditis elegans repo-1 (37% identical).
Diseases named in the same sentence as SF3A2 in open-access papers:
SF3A2 is named in the same sentence as 20 diseases in open-access papers, as found by Europe PMC text mining. Sharing a sentence is not in itself a finding about the gene and the disease. The quoted sentences say what the papers report.
colorectal cancer (2 papers, 2025 to 2026). A primary or metastatic malignant neoplasm that affects the colon or rectum. "Three highly expressed, colorectal cancer-biased chimeric RNAs, RRM2-C2orf48, METTL21B-TSFM, and SF3A2-AMH, were validated by RT-PCR and Sanger sequencing." (PMID 41155268, 2025).
myelodysplastic syndrome (2 papers, 2019). A clonal hematopoietic disorder characterized by dysplasia and ineffective hematopoiesis in one or more of the hematopoietic cell lines. "SF3A2 is part of the U2 snRNP, and another member of this complex (SF3B1) is recurrently mutated in myelodysplastic syndrome, acute myeloid leukemia, and chronic lymphocytic leukemia." (PMID 30867899, 2019).
myocardial infarction (2 papers, 2021 to 2023). Gross necrosis of the myocardium, as a result of interruption of the blood supply to the area, as in coronary thrombosis. "A recent study has shown that SF3A2 as new susceptibility gene for myocardial infarction.In our study, proteome and experimental data identified that SF3A2 could positively regulate NLRP3 inflammasome activation and cell pyroptosis." (PMID 36732831, 2023).
colon cancer (1 paper, 2026). "To evaluate SF3A2's impact on colon cancer cells within living organisms, we developed tumor xenograft models." (PMID 41399366, 2026).
Diamond-Blackfan anemia (1 paper, 2019). A congenital aregenerative and often macrocytic anemia with erythroblastopenia. "In addition, our studies suggest that at least SF3A2, and potentially other regulators such as some implicated mRNA translation factors, may be key disease modifiers that alter the impaired erythropoiesis seen in diseases like MDS or Diamond-Blackfan anemia." (PMID 31070582, 2019).
myocardial ischemia (1 paper, 2026). A disorder of cardiac function caused by insufficient blood flow to the muscle tissue of the heart. "In addition, SF3A2 had a pivotal role in the pathophysiology of myocardial ischemia reperfusion injury." (PMID 41399366, 2026).
osteosarcoma (1 paper, 2019). A usually aggressive malignant bone-forming mesenchymal neoplasm, predominantly affecting adolescents and young adults. "The HR value of SF3A2 was 1.051, and SF3A2 was also reported to be associated with the metastasis and recurrence of osteosarcoma." (PMID 32063918, 2019).
renal carcinoma (1 paper, 2021). A carcinoma arising from the epithelium of the renal parenchyma or the renal pelvis. "SF3A2 stimulates inclusion of exon 14 of the histone methyltransferase enhancer of zeste 2 polycomb repressive complex 2 subunit (EZH2) and has pro‐proliferative activity in renal cancer." (PMID 34586744, 2021).
triple-negative breast carcinoma (1 paper, 2025). An invasive breast carcinoma which is negative for expression of estrogen receptor (ER), progesterone receptor (PR), and human epidermal growth factor receptor 2 (HER2). "SF3A2 and SNIP1 have been identified as crucial mediators implicated in the invasion of triple-negative breast cancer." (PMID 40134434, 2025).
viral infection (1 paper, 2016). "In contrast to the effect observed with components of U5, silencing a core component of U2 snRNP (SF3A2) greatly reduced viral replication, supporting the idea that viral modulation of cellular splicing must be specific to provide a beneficial environment for viral infection." (PMID 27575636, 2016).
infection (4 papers, 2016 to 2025). The state of being infected such as from the introduction of a foreign agent such as serum, vaccine, antigenic substance or organism. "We achieved similar infection (30–40% on day 6) at the early time points between controls (shLuc) and shRNAs targeting SF3A2." (PMID 31070582, 2019). "In contrast, no significant changes were observed for CD2BP2, DDX23, EFTUD2, SNRNP40 (U5 snRNP components) or SF3A2 (U2 snRNP component) levels up to 48 hours of infection as compared with those in uninfected cells." (PMID 27575636, 2016). "RUVBL2, ADNP, SF3A2, CDK2, PRKDC, and NONO were particularly interesting as the increase in acetylation following SIRT2 inhibition temporally aligned with the time point of maximal interaction with SIRT2 during infection." (PMID 37916830, 2023).
tumor (4 papers, 2020 to 2026). "SF3A2 was considered as a critical mediator of tumor aggressiveness because of its association with poor patient prognosis." (PMID 41399366, 2026). "The results indicated that SF3A2 was negatively linked to StromalScore, ESTIMATEScore, and ImmuneScore in most tumor types from TCGA." (PMID 41399366, 2026). "Since the immune microenvironment markedly shapes tumor progression and offers insights into cancer immunotherapy strategies, we investigated the association between SF3A2 and the tumor immune landscape." (PMID 41399366, 2026). "Subsequently, to evaluate the potential role of SF3A2 in tumor immune evasion, we analyzed its correlation with the TIDE score using transcriptomic data from TCGA CRC cohort." (PMID 41399366, 2026). "Our study revealed a significant correlation between elevated SF3A2 expression and an immunosuppressive tumor microenvironment (TME) in CRC." (PMID 41399366, 2026). "Immunostaining with validated SF3A2 antibodies demonstrated increased SF3A2 levels in tumor tissue relative to normal tissue." (PMID 41399366, 2026). "Research examining SF3A2's tumor-related mechanisms remained sparse." (PMID 41399366, 2026). "Further supporting the dysfunctional immune state, our TIDE (Tumor Immune Dysfunction and Exclusion) analysis revealed significantly higher TIDE scores in patients with high SF3A2 expression." (PMID 41399366, 2026). "We found that SF3A2 (splicing factor 3A2) was downregulated in apatinib-treated tumor xenograft tissues compared with that without apatinib treatment, and silencing of SF3A2 increased circRACGAP1 expression." (PMID 32139670, 2020).
cancer (3 papers, 2019 to 2026). A tumor composed of atypical neoplastic, often pleomorphic cells that invade other tissues. "The association of SF3A2, a core component of the spliceosome's SF3a complex, with cancer progression and an immunosuppressive TME is a novel and intriguing finding." (PMID 41399366, 2026). "To investigate SF3A2's interaction with the immune microenvironment across various cancers, we assessed the associations between SF3A2 levels and immune cell populations using ESTIMATE algorithms." (PMID 41399366, 2026). "Interestingly, and highlighting the context-dependent role of SF3A2, elevated SF3A2 expression was associated with extended OS in several other cancer types, including TGCT, CESC, PAAD, STAD, THYM, UCEC, and UVM patients." (PMID 41399366, 2026). "In this study, the upregulation of SF3A2 in CRC was identified through TMT-based quantitative proteomic screening of surgically resected paired primary cancer and normal epithelial tissues." (PMID 41399366, 2026). "Furthermore, examining SF3A2's pan-cancer prognostic implications through Kaplan-Meier survival assessment revealed that increased SF3A2 corresponded to diminished OS in ACC, KIRP, LIHC, LUAD, MESO, PCPG, SARC patients." (PMID 41399366, 2026). "While SF3A2's primary role is in pre-mRNA splicing, its dysregulation in cancer may have profound downstream consequences." (PMID 41399366, 2026). "Utilizing TCGA database resources, we investigated SF3A2 gene expression across diverse human cancer types versus normal specimens." (PMID 41399366, 2026). "Nevertheless, research on SF3A2 remains limited, and its cancer-related functions are not well defined." (PMID 41399366, 2026).
SF3A2 also shares sentences with these, for which no sentence is quoted: acute myeloid leukemia (1 paper); breast carcinoma (1); chronic lymphocytic leukemia (1); Erythropoiesis (1); lung disease (1); nematode infection (1); prostate carcinoma (1).